ARMC1 (armadillo repeat containing 1)
Description:
In association with mitochondrial contact site and cristae organizing system (MICOS) complex components and mitochondrial outer membrane sorting assembly machinery (SAM) complex components may regulate mitochondrial dynamics playing a role in determining mitochondrial length, distribution and motility.
Synonyms: ARCP; FLJ10511
Tractability: PROTAC: ubiquitination databases record sites on it; its protein half-life has been measured.
Gene: Protein-coding gene on chromosome 8 (65,602,456 to 65,634,217, reverse strand). Ensembl gene ENSG00000104442.
Subcellular location: Cytoplasm; Mitochondrion; Mitochondrion outer membrane
Subcellular location (Human Protein Atlas): Mitochondria
Gene Ontology:
Molecular function: protein binding; metal ion binding
Biological process: intracellular distribution of mitochondria
Cellular component: cytoplasm; cytosol; mitochondrial outer membrane; mitochondrion
Genetic constraint (gnomAD): Loss-of-function variants: 12 observed, 21.96 expected, observed/expected ratio (o/e) 0.55, 90% interval 0.35 to 0.88. The upper end of that interval is the gene's LOEUF score, 0.88, which puts it in group 3 of 6, group 1 being the genes least tolerant of losing a copy. Missense variants: 223 observed, 309.04 expected, observed/expected ratio (o/e) 0.72, 90% interval 0.65 to 0.81. Synonymous variants: 103 observed, 109.73 expected, observed/expected ratio (o/e) 0.94, 90% interval 0.8 to 1.11.
Homologues: Orthologues: chimpanzee ARMC1 (100% identical), macaque ARMC1 (100% identical), pig ARMC1 (99% identical), dog ARMC1 (99% identical), rabbit ARMC1 (99% identical), mouse Armc1 (98% identical), guinea pig ARMC1 (98% identical), rat Armc1 (98% identical), tropical clawed frog armc1 (84% identical), zebrafish armc1 (77% identical).
Diseases named in the same sentence as ARMC1 in open-access papers:
ARMC1 is named in the same sentence as 6 diseases in open-access papers, as found by Europe PMC text mining. Sharing a sentence is not in itself a finding about the gene and the disease. The quoted sentences say what the papers report.
hepatocellular carcinoma (1 paper, 2015). A malignant tumor that arises from hepatocytes. "For example, a mRNA of miR-452, ARMC1 is up-regulated and frequently amplified in human hepatocellular carcinoma." (PMID 25707620, 2015).
mastitis (1 paper, 2024). Inflammation of breast tissue during lactation or postpartum due to an obstructed duct or infection. "In addition, a few studies on mammary gland transcriptome and proteome in sheep and cows with clinical mastitis have detected ARMC1 as a differentially expressed gene, indicating its potential involvement in the immune response to mammary gland infections." (PMID 39335302, 2024).
cancer (2 papers, 2020 to 2021). A tumor composed of atypical neoplastic, often pleomorphic cells that invade other tissues. "The expression plots between signature ARMC1 and signature UTP23 show that they are associated with each other, and that they are co-amplified in 76.2% of the cancer cases." (PMID 33057153, 2020).
ARMC1 also shares sentences with these, for which no sentence is quoted: breast carcinoma (1 paper); dyslipidemia (1); tumor (1).